HYLS1 (HYLS1 centriolar and ciliogenesis associated)
Description:
Plays a role in ciliogenesis.
Synonyms: HLS; FLJ32915
Tractability: Antibody: its Gene Ontology location is reachable by antibodies, with high confidence. PROTAC: ubiquitination databases record sites on it.
Gene: Protein-coding gene on chromosome 11 (125,883,614 to 125,900,846, forward strand). Ensembl gene ENSG00000198331.
Subcellular location: Cytoplasm; Cell projection, cilium; Cytoplasm, cytoskeleton, microtubule organizing center, centrosome; Cytoplasm, cytoskeleton, microtubule organizing center, centrosome, centriole
Subcellular location (Human Protein Atlas): Cytosol; Plasma membrane
Gene Ontology:
Molecular function: protein binding
Biological process: cilium assembly
Cellular component: centrosome; cytoplasm; cytosol; nucleus; centriole; cilium; non-motile cilium
Genetic constraint (gnomAD): Loss-of-function variants: 25 observed, 30.84 expected, observed/expected ratio (o/e) 0.81, 90% interval 0.59 to 1.13. The upper end of that interval is the gene's LOEUF score, 1.13, which puts it in group 4 of 6, group 1 being the genes least tolerant of losing a copy. Missense variants: 352 observed, 384.74 expected, observed/expected ratio (o/e) 0.91, 90% interval 0.84 to 1. Synonymous variants: 128 observed, 134.84 expected, observed/expected ratio (o/e) 0.95, 90% interval 0.82 to 1.1.
Gene-disease validity (ClinGen):
ClinGen rates the evidence that HYLS1 causes each of these diseases.
hydrolethalus syndrome (autosomal recessive): Moderate. Hydrolethalus (HLS) is a severe fetal malformation syndrome characterized by craniofacial dysmorphic features, central nervous system, cardiac, respiratory tract and limb abnormalities.
Homologues: Orthologues: chimpanzee HYLS1 (99% identical), macaque HYLS1 (97% identical), dog HYLS1 (88% identical), rabbit HYLS1 (88% identical), pig HYLS1 (87% identical), rat Hyls1 (82% identical), mouse Hyls1 (82% identical), guinea pig HYLS1 (81% identical), zebrafish hyls1 (31% identical), tropical clawed frog hyls1 (27% identical).
Diseases named in the same sentence as HYLS1 in open-access papers:
HYLS1 is named in the same sentence as 14 diseases in open-access papers, as found by Europe PMC text mining. Sharing a sentence is not in itself a finding about the gene and the disease. The quoted sentences say what the papers report.
hydrolethalus syndrome (6 papers, 2020 to 2024). "A mutation in HYLS1 causes hydrolethalus syndrome characterized by developmental defects of the fetal brain and heart." (PMID 38167462, 2024). "HYLS1 is associated with Hydrolethalus syndrome, a disorder characterized by HC and craniofacial abnormalities." (PMID 38439105, 2024). "These include Pallister‐Hall syndrome (PHS), as well as HPE9 and Culler‐Jones syndrome (CJS), due to dominant mutations in the GLI3 and GLI2 genes, respectively, and hydrolethalus syndrome related to recessive mutations in HYLS1 and KIF7." (PMID 31840946, 2020). "HYLS1 is an evolutionarily conserved centriole protein, which is critical for ciliogenesis, and its mutation causes ciliopathy–hydrolethalus syndrome." (PMID 32509774, 2020). "Hydrolethalus syndrome (HLS) is a rare recessive lethal inherited disorder that causes serious defects in fetal development and results in birth defects, with its causal gene HYLS1 first identified in 2005." (PMID 32509774, 2020).
ciliopathy (5 papers, 2016 to 2024). A genetic disorder of the cellular cilia or the cilia anchoring structures, the basal bodies, or of ciliary function. "In sum, we provide mechanistic insights into how the ciliopathy protein HYLS-1 contributes to ciliogenesis and establishment of the ciliary gate." (PMID 27534274, 2016). "Furthermore, AlphaFold-based mutagenesis analyses suggest that the ciliopathy-related residue D211 of HYLS1 interacts with the CTT of TUBB and suppresses its inhibitory role in incomplete tubule formation." (PMID 38519454, 2024). "AlphaFold-based structural models and mutagenesis analyses further suggest that the ciliopathy-related residue D211 of HYLS1 physically traps the wobbling C-terminal tail of TUBB, thereby suppressing its inhibitory role in the initiation of the incomplete microtubule assembly." (PMID 38519454, 2024). "Besides KIAA0586, HYLS1 and KIF7 are also known for being causative of ciliopathies, indicating that all three genes may have similar or converging genomic pathways." (PMID 39063141, 2024).
Cirrhosis (1 paper, 2012). A chronic disorder of the liver in which liver tissue becomes scarred and is partially replaced by regenerative nodules and fibrotic tissue resulting in loss of liver function. "Most cell structure related genes were up-regulated in initial fibrosis (HYLS1, MAP6D1 and TOR1AIP1) and genes related to cell adhesion, cell cycle and signaling showed differential expression in both initial fibrosis and cirrhosis." (PMID 22397681, 2012).
neuroblastoma (1 paper, 2009). Neuroblastoma (NB) is the most common solid, extracranial childhood tumor. "For this, wt and mutant HYLS1 in fusion with the Gal4-DBD as well as the reporter vector pG5LUC were transiently expressed in the SH-SY5Y neuroblastoma cells." (PMID 19400947, 2009).
schizophrenia (1 paper, 2024). A major psychotic disorder characterized by abnormalities in the perception or expression of reality. "Integrating HC ELEs with GWAS and gene regulatory networks further helps pinpoint previously undescribed but functionally relevant genes for BMI (e.g., CDK5, HSD11B1) and schizophrenia (e.g., HYLS1, PMM2)." (PMID 38167462, 2024). "Both HYLS1 and PMM2 have not been implicated in GWAS, but their neural-cardiac roles are relevant to schizophrenia." (PMID 38167462, 2024).
malformation syndrome (1 paper, 2009). "The results presented here add a significant amount of new information of the HLS pathogenesis and although the subject of the study is a rare malformation syndrome, these findings strongly suggest an essential role for HYLS1 in normal fetal development." (PMID 19400947, 2009).
HYLS1 also shares sentences with these, for which no sentence is quoted: diabetes (1 paper); fibrosis (1); Hydrocephalus (1); Infertility (1); Joubert syndrome (1); lung carcinoma (1); male infertility (1); primary ciliary dyskinesia (1).